RNU6-450P (RNA, U6 small nuclear 450, pseudogene)
Gene: Small nuclear RNA gene on chromosome 17 (59,847,438 to 59,847,544, reverse strand). Ensembl gene ENSG00000201524.
Homologues: Orthologues: chimpanzee U6 (99% identical), macaque U6 (85% identical), pig U6 (71% identical), guinea pig U6 (68% identical), dog U6 (67% identical), mouse Gm55922 (64% identical). Paralogues in human: RNU6-428P (81% identical), RNU6-454P (81% identical), RNU6-774P (81% identical), RNU6-87P (81% identical), RNU6-1329P (80% identical), RNU6-16P (80% identical), RNU6-812P (80% identical), RNU6-1005P (79% identical), RNU6-1179P (79% identical), RNU6-11P (79% identical), RNU6-1209P (79% identical), RNU6-144P (79% identical), and 1286 more.